INS (insulin)
Diseases named in the same sentence as INS in open-access papers (continued):
Sharing a sentence is not in itself a finding about the gene and the disease.
diabetes (continued). "UA affects the risk of diabetes by affecting glucose metabolism and insulin secretion of pancreatic β-cells." (PMID 36545489, 2022). "Diabetes mellitus, a metabolic disease characterized by hyperglycaemia and endogenous insulin hypersecretion or resistance, is an independent risk factor for cardiovascular disease, and a large number of diabetic patients die suddenly due to AMI." (PMID 36460963, 2022). "Diabetes mellitus is known as the most common endocrine disorder that occurs through hyperglycemia following the deficiency of insulin production or function." (PMID 35366956, 2022). "Diabetes mellitus is a group of physiological dysfunctions characterized by a hypoglycemic state, insulin deficiency, inadequate insulin secretion, or excessive glucagon secretion." (PMID 36615695, 2022). "Diabetes mellitus (DM) is a metabolic disease characterized by chronic hyperglycemia caused by deficiency of insulin secretion or impairment of insulin action." (PMID 35273587, 2022). "In the normoprolactinemic population in general, higher PRL levels within the normal range were associated with improved insulin sensitivity and glucose metabolism, and lower prevalence of diabetes and metabolic syndrome." (PMID 36704037, 2022). "Diabetes mellitus is defined by persistent hyperglycemia, which affects carbohydrate, lipid, and protein metabolism and comes from a deficiency in the production of insulin, the action of insulin, or both conjugates." (PMID 36675992, 2022). "Diabetes mellitus (DM) is a metabolic condition that is caused by problems in insulin production, its action, or both." (PMID 36158357, 2022). "Diabetes is a chronic metabolic diseases caused by deficiency in insulin secretion and insulin resistance." (PMID 35056765, 2022). "C-peptide is inversely associated with glycaemic variability and post-meal glucose rise in both Type 1 and Type 2 diabetes and is inversely associated with response to prandial insulin in experimental conditions in a mixed population with diabetes." (PMID 35574003, 2022). "Comparison of clinical characteristics of children with diabetes caused by a mutation in INS, KCNJ11, or ABCC8." (PMID 35518939, 2022). "Scattered small cross-sectional studies have shown that exercise capacity is inversely associated with impaired glycemic control, the metabolic syndrome, diabetes and positively associated with glucose disposal rate and insulin sensitivity." (PMID 36451187, 2022). "The one technology that was associated significantly with a duration of diabetes of more than 10 years was the insulin pump." (PMID 35719798, 2022). "Diabetes mellitus has been estimated to be the fifth leading cause of death globally, characterized by hyperglycemia due to defects in insulin action, insulin secretion, or both." (PMID 35408574, 2022). "Type 2 diabetes mellitus (T2D) is a globally ubiquitous metabolic disease characterized by hyperglycemia that is caused by reduced insulin sensitivity in target tissues and impaired insulin secretion from pancreatic β-cells." (PMID 35145074, 2022). "Diabetes is often associated with a decline in insulin sensitivity or pancreatic β-cell dysfunction with decreased insulin production to maintain glucose homeostasis." (PMID 36060809, 2022). "On the other hand, streptozotocin (STZ) inhibits insulin secretion and causes insulin-dependent diabetes mellitus due to its specific chemical properties, namely, alkylating potency." (PMID 36496564, 2022). "Earlier diabetes onset and higher daily insulin dosage were associated with body fat % difference between children with T1D and TDC." (PMID 35813369, 2022). "In order to evoke insulin-deficient diabetes in mice, the animals were injected with streptozotocin (STZ), which destroys the pancreatic beta cells." (PMID 35327418, 2022).
diabetes (continued). "Blood pressure increases in diabetic patients are known to be twice more than in non-diabetic patients and patients with hypertension are often resistant to insulin and are more prone to the risk of diabetes than normal people." (PMID 35655125, 2022). "Metformin is considered a first-line anti-diabetes agent, decreases insulin and insulin-associated factors, inhibits mitochondrial function, improves the metabolic and cellular processes, and cellular senescence." (PMID 35572534, 2022). "Latinx adults have been shown to believe that the use of insulin signals advanced diabetes and is associated with the onset of complications, including blindness and toe amputations." (PMID 35444916, 2022). "Studies have also shown that catechins can effectively control hyperglycemia and prevent diabetes complications by improving insulin sensitivity as well as reducing risk factors for T2D, such as dyslipidemia, obesity, and oxidative stress." (PMID 36232871, 2022). "In most cases, it presents as fulminant diabetes associated with diabetic ketoacidosis, suggesting acuity and rapid onset, with a sudden decline in insulin secretory function." (PMID 36612243, 2022). "The impairment or loss of islet cell function is the direct cause of diabetes, and lncRNAs play an important role in regulating insulin-secreting β islet cells." (PMID 36225311, 2022). "While most of the participants knew about diabetes as a disease, but only half of them knew about the association of glucose and insulin with diabetes." (PMID 36466517, 2022). "Generally, a stimulated C-peptide of <0.2 nmol/l in plasma or 0.2 nmol/mol in urine in people with diabetes indicates severe insulin deficiency and, therefore, permanent insulin requirement." (PMID 35462815, 2022). "This is also true for insulin-treated diabetes, which also associates with greater graft detachment and rebubbling rates." (PMID 35999622, 2022). "The Diabetes Eating Problems Survey‐R (DEPS‐r) is a diabetes‐specific measure of DEBs that includes food restriction/dysregulation, weight loss, insulin reduction/omission, and vomiting." (PMID 35751499, 2022). "Increased intake of whole-grain foods has been related to a reduced risk of developing diabetes and heart disease, with one underlying pathway for this relation attributed to increased insulin sensitivity." (PMID 36556161, 2022). "In healthy people and patients with early diabetes, irisin has generally been negatively associated with insulin levels." (PMID 35040046, 2022). "The disease is characterized by chronic hyperglycemia due to inadequate insulin secretion or reduced insulin sensitivity." (PMID 36408221, 2022). "Diabetes mellitus is a glucose, lipid, protein, and water and electrolyte metabolism syndrome caused by IR or insufficient insulin secretion." (PMID 35885283, 2022). "Diabetes mellitus is a worldwide known disease caused by the failure of the pancreas to generate insulin or dysfunction of the human system to use insulin properly and has been emerging very rapidly worldwide." (PMID 35720184, 2022). "Diabetes is a metabolic disease, the pathophysiology is linked to insulin levels in the body and the body's ability to use insulin." (PMID 35237647, 2022). "Theoretically, childbirth significantly affects physiological indicators such as metabolism, insulin secretion, and insulin sensitivity in women, which in turn is associated with diabetes." (PMID 35559347, 2022). "Type 1 diabetes mellitus (T1DM) is a chronic condition caused by deterioration in the ability of the pancreas to produce insulin, leading to insufficient insulin levels." (PMID 35830220, 2022). "Diabetes mellitus (DM) is a chronic disease characterized by hyperglycemia, caused either by impaired insulin secretion or insulin function." (PMID 36309772, 2022).
diabetes (continued). "Diabetes mellitus (DM) is a group of metabolic diseases characterized by chronic hyperglycemia caused by one of two defects: a defect in insulin secretion or a defect in insulin action, or both." (PMID 35619957, 2022). "Disruption of CLOCK and BMAL1 was previously shown cause to hypoinsulinaemia and diabetes in mice, and changes in the synchronization of the beta cells, resulting in loss of pulsatile or first phase insulin secretion, are predictive for both T1D and T2D." (PMID 36589856, 2022). "Type II diabetes mellitus (DM2), accounting for about 90% of all cases of diabetes, is caused by a decrease in insulin sensitivity in target organs, such as the liver, muscle, and adipose tissue, as well as a deficiency in insulin secretion." (PMID 36362322, 2022). "Diabetes mellitus is a metabolic disorder caused by insufficient insulin secretion by islet β-cells, and insulin secretion by islet β-cells mainly depends on the production of mitochondrial ATP stimulated by glucose." (PMID 35590379, 2022). "Diabetes is a common metabolic disease characterized by hyperglycemia owing to insulin secretion deficiency for type 1 diabetes (T1D) or insulin resistance for type 2 diabetes (T2D), which has become a global health problem." (PMID 36014349, 2022). "Insulin release increases by 40–70% in individuals at high risk of T2D or with newly diagnosed diabetes." (PMID 35806437, 2022). "GPx3 expression reduces extracellular H2O2 concentration in human muscle cells regulating H2O2 levels and its function as a second messenger, and the inhibition of GPx3 is associated with unbalance in the redox system, insulin resistance and diabetes mellitus." (PMID 35205224, 2022). "There are no studies reporting effects of SCT in HIV patients on the level of physical activity, insulin secretion, insulin resistance, and risk of diabetes." (PMID 35167170, 2022). "Diabetes, as a global chronic disease among millions of people, is caused by the inability to produce insulin because of pancreatic dysfunction (type I diabetes) or caused by the malfunction of cells to use insulin (type II diabetes)." (PMID 36349339, 2022). "While each type of diabetes is associated with different etiologies, all ultimately result in the death and/or dysfunction of the pancreatic insulin-producing β cell." (PMID 36339450, 2022). "The UK Prospective Diabetes Study (UKPDS) demonstrated that intensive glycemic control with SUs or insulin significantly reduces macrovascular complications associated with improved glycemic control." (PMID 35252271, 2022). "In conclusion, L-arginine supplementation can improve glucose tolerance and insulin sensitivity, reduce inflammation and oxidative stress, and even lower the risk of diabetes." (PMID 36297315, 2022). "The likely reason for this association is that prolonged diabetes can decrease insulin hormone production by the pancreas or result in target cell resistance." (PMID 36227943, 2022). "Human type 1 diabetes mellitus is a chronic autoimmune disease characterized by the selective loss of insulin-producing β-cells in pancreatic islets of genetically susceptible individuals." (PMID 35159301, 2022). "Diabetes mellitus is a diverse condition caused by progressively impaired insulin production from β-cells and insulin resistance in target tissues." (PMID 36430158, 2022). "Among which, type 2 diabetes mellitus (T2DM) is caused by the inability of β cells to produce enough insulin to overcome systemic insulin resistance and is usually associated with obesity, inactivity, and aging." (PMID 36620773, 2022). "The first category of diabetes (T1DM) is typically associated with failure in insulin production resulting from the destruction of pancreatic β-cells by T-cell-mediated autoimmunity." (PMID 35054888, 2022).
diabetes (continued). "The PI3K/AKT signaling pathway is closely linked to the occurrence of diabetes and a decrease in insulin sensitivity; the activation of the PI3K/AKT pathway is blunted with the occurrence of insulin resistance." (PMID 35571083, 2022). "The role of insulin and leptin hormones in memory and cognitive function, which are conventionally linked to diabetes and obesity, is attracting more and more attention." (PMID 36505102, 2022). "Diabetes Mellitus is a metabolic disease that is associated with disorders in the metabolism of carbohydrates, proteins, and lipids that affect insulin action." (PMID 35669072, 2022). "Diabetes mellitus is characterized by metabolic abnormalities due to insufficient insulin production due to loss of beta cells (type 1 diabetes) or abnormalities in the insulin receptor protein itself (type 2 diabetes)." (PMID 35955522, 2022). "The American Diabetes Association recommends multiple measurements daily for the assessment of glucose levels, especially for patients receiving insulin therapy." (PMID 35271177, 2022). "During insulin resistance (IR), glucose metabolism converges in mitochondria via insulin signalling causing diabetes progression." (PMID 35246121, 2022). "Obesity-induced increase in IL-1β levels, mostly in diabetes patients, and the improvement in insulin sensitivity was associated with decrease in cytokine levels." (PMID 35889863, 2022). "Dysregulation of insulin signaling causes a variety of human diseases including diabetes, insulinoma, metabolic syndrome, ovary syndrome, and auto-immune disorders." (PMID 35480325, 2022). "Similar effects have been observed for other models of diabetes including the leptin deficient ob/ob model, the Akita model of impaired insulin folding, and even the type 1 diabetes, streptozotocin (STZ) model." (PMID 35355560, 2022). "Inflammation in diabetes and its related metabolic disorders are known to cause disturbances in insulin signaling." (PMID 36531176, 2022). "For example, overweight and obese PCO patients are characterized by increased insulin secretion and reduced insulin sensitivity but have an increased risk of developing diabetes." (PMID 36615676, 2022). "It is reasonable to assume that even with GCGR mutations in β cells, glucagon binding to GLP-1R exerts an insulin-promoting effect that can reduce blood glucose concentrations in patients with diabetes." (PMID 35784565, 2022). "Autoantibodies (Ab) to glutamic decarboxylase (GAD), insulinoma-associated antigen 2 (IA-2), zinc transporter 8 (ZnT8) and insulin are used widely to identify β-cell autoimmunity in diabetes." (PMID 34533636, 2022). "Diabetes mellitus (DM) is a chronic metabolic disorder caused by insufficient insulin secretion, impaired insulin action, or a combination of the two, resulting in hyperglycemia." (PMID 36064352, 2022). "In particular, the administration of empagliflozin in individuals with prediabetes or diabetes was associated with the amelioration of glycemia and insulin sensitivity and with increased β-hydroxybutyrate (BHB) levels." (PMID 35265043, 2022). "A previous study on type 1 diabetes mellitus showed that basal insulin analogs are superior to NPH with respect to risk reduction in nocturnal and severe hypoglycemia." (PMID 35890301, 2022). "Diabetes is a chronic disease caused by defective insulin secretion in the body, resulting in metabolic abnormalities with persistent blood glucose elevation." (PMID 35178452, 2022). "Diabetes mellitus is a metabolic disorder characterized by chronic hyperglycemia caused by a deficiency of the hormone insulin or by ineffective use of insulin in the body." (PMID 35630761, 2022). "Both forms of diabetes eventually lead to progressive loss of pancreatic β cells and insufficient insulin secretion." (PMID 36383675, 2022). "Reducing insulin levels and the risk of developing diabetes can be accomplished by modifying one's eating habits and level of exercise, along with Metformin." (PMID 36299963, 2022).
diabetes (continued). "For the first time, we have explored effects of various diets and drug treatments other than insulin on diabetes-associated bladder enlargement; many of them had differential effects on glucose levels and bladder enlargement." (PMID 36003651, 2022). "It has been shown that the diabetes-related SNPs were mainly observed in genes which were associated with immune system, nuclear receptors, and insulin signaling pathway." (PMID 35366956, 2022). "Since vitamin D is necessary for healthy insulin secretion and reduces abnormal insulin resistance through known mechanisms, vitamin D deficiency has long been thought likely to increase type 2 diabetes mellitus (T2DM) risks." (PMID 35745248, 2022). "One reported that intensive blood-glucose control by either sulphonylureas or insulin substantially decreased the risk of microvascular complications." (PMID 35795563, 2022). "Type 1 diabetes mellitus (T1DM) is characterized by the absolute deficiency of endogenous insulin and requires exogenous insulin for survival." (PMID 35898377, 2022). "NF-kappa B signaling, diabetes, and insulin-linked pathways all saw an increase in attention during this period." (PMID 35813951, 2022). "Diabetes is a metabolic disease that is caused by hyperglycemia due to the deficiency of insulin secretion or insulin action (or both in some cases)." (PMID 36139935, 2022). "While control animals showed a progressive development of diabetes (hyperglycemia, severely impaired glucose tolerance, impaired insulin secretion), β cell LATS2-deficient mice showed milder changes in diabetes development induced by low doses of STZ." (PMID 35054822, 2022). "As mitochondrial metabolism is a major determinant of β-cell insulin secretion, mitochondrial dysfunction underlies β-cell failure and type 2 diabetes mellitus progression." (PMID 35909530, 2022). "These mice had normal islet cell mass at baseline but were protected from chemically-induced diabetes, with reduced loss of islet cell area and insulin secretion." (PMID 35714079, 2022). "In a broader sense, the causative factors of diabetes can reside in insulin resistance, abnormal insulin secretion and hepatic glucose synthesis along with impaired fat metabolism." (PMID 35282429, 2022). "The current standard of care for individuals with GDM or T2DM during pregnancy includes lifestyle interventions as well as insulin or metformin therapy." (PMID 35099411, 2022). "Type 2 diabetes mellitus (T2D) is a metabolic disease characterized by high blood glucose levels resulting from a deficiency in insulin synthesis, insulin resistance, or both." (PMID 36144408, 2022). "Type 1 diabetes mellitus (T1DM) is a chronic autoimmune characterized by hyperglycemia due to loss of insulin producing cells of the pancreas that can end in diabetic coma and eventually death." (PMID 35915454, 2022). "In general, diabetes mellitus is associated with relative or absolute impairment of insulin secretion and varying degrees of peripheral resistance to insulin." (PMID 35386152, 2022). "During hyperinsulinemia, the efficiency of insulin signaling is inhibited, resulting in reduced glucose uptake from the blood, which increases the risk of diabetes." (PMID 36992743, 2022). "The American Diabetes Association recommends combining several insulin products for juvenile patients with type 1 diabetes and adults with difficult-to-control blood glucose levels." (PMID 35431962, 2022). "Common DMPs with diabetes epigenome-wide association studies from other populations suggest a partially common epigenomic signature of glucose and insulin activity." (PMID 36529747, 2022). "As claimed by the American Diabetes Association, the capacity of insulin to simultaneously regulate numerous genes through a transcription factor provides the best explanation for its integrated effects on various cellular activities." (PMID 36381916, 2022).